DOP1B (DOP1 leucine zipper like protein B)
Description:
May play a role in regulating membrane trafficking of cargo proteins. Together with ATP9A and MON2, regulates SNX3 retromer-mediated endosomal sorting of WLS away from lysosomal degradation.
Synonyms: C21orf5; DOPEY2; KIAA0933; 21orf5
Tractability: Antibody: UniProt places it where antibodies can reach, with medium confidence. PROTAC: ubiquitination databases record sites on it.
Safety:
Unwanted effects reported when the protein is acted on. In parentheses: how it was acted on, where the effect was seen, and who reports it.
neutropenia (source: ClinPGx)
Gene: Protein-coding gene on chromosome 21 (36,156,758 to 36,294,275, forward strand). Ensembl gene ENSG00000142197.
Subcellular location: Early endosome membrane; Golgi apparatus membrane
Subcellular location (Human Protein Atlas): Nucleoplasm; Mitochondria
Gene Ontology:
Molecular function: protein binding
Biological process: cognition; embryonic pattern specification; endoplasmic reticulum organization; Golgi to endosome transport; regulation of retrograde transport, endosome to Golgi
Cellular component: early endosome membrane; extracellular exosome; endosome; Golgi apparatus; Golgi membrane; trans-Golgi network; cytosol
Genetic constraint (gnomAD): Loss-of-function variants: 164 observed, 224.78 expected, observed/expected ratio (o/e) 0.73, 90% interval 0.64 to 0.83. The upper end of that interval is the gene's LOEUF score, 0.83, which puts it in group 3 of 6, group 1 being the genes least tolerant of losing a copy. Missense variants: 2,511 observed, 2,810.7 expected, observed/expected ratio (o/e) 0.89, 90% interval 0.86 to 0.92. Synonymous variants: 1,136 observed, 1,175.7 expected, observed/expected ratio (o/e) 0.97, 90% interval 0.92 to 1.01.
Homologues: Orthologues: chimpanzee DOP1B (99% identical), macaque DOP1B (96% identical), dog DOP1B (90% identical), rabbit DOP1B (88% identical), mouse Dop1b (86% identical), rat Dop1b (86% identical), guinea pig DOP1B (85% identical), pig DOP1B (83% identical), tropical clawed frog dop1b (70% identical), zebrafish dop1b (37% identical), Drosophila melanogaster CG15099 (32% identical), Caenorhabditis elegans pad-1 (25% identical). Paralogues in human: DOP1A (40% identical).
Diseases named in the same sentence as DOP1B in open-access papers:
DOP1B is named in the same sentence as 7 diseases in open-access papers, as found by Europe PMC text mining. Sharing a sentence is not in itself a finding about the gene and the disease. The quoted sentences say what the papers report.
Down syndrome (5 papers, 2012 to 2024). "The DOP1B gene has been considered a candidate gene for human brain abnormalities and mental retardation in Down syndrome and Peters anomaly." (PMID 38818041, 2024). "The DOP1B gene is a member of the Dopey gene family and has been investigated in neuroscience because of its location on chromosome 21, the same region of Down syndrome, which is a 21 trisomy." (PMID 39238827, 2024). "It was also observed that there was overexpression of DOP1B in the Down syndrome brain regions, and DOP1B was considered a candidate gene for Down syndrome." (PMID 38818041, 2024).
Peters anomaly (1 paper, 2024). Peters anomaly (PA) is a congenital corneal opacity disorder characterized by a central corneal leukoma that obstructs the pupil leading to visual loss as well as absence of the posterior corneal stroma and Descemet membrane. "DOP1B has been identified as a candidate gene for Peters anomaly (PA), and its expression can be detected in the ocular tissues of a PA patient such as the cornea, sclera, iris, lens, and retina." (PMID 39238827, 2024).
DOP1B also shares sentences with these, for which no sentence is quoted: mental retardation (5 papers); neurodegenerative disease (2); intellectual impairment (1); Rett syndrome (1); schizophrenia (1).